INS (insulin)
Diseases named in the same sentence as INS in open-access papers (continued):
Sharing a sentence is not in itself a finding about the gene and the disease.
Obesity (continued). "Several studies have demonstrated that subjects with PWS, not receiving hGH therapy, had lower insulin levels and greater insulin sensitivity compared to controls matched for degree of obesity." (PMID 23962041, 2013). "This conclusion is based in part on the observation that lean, formerly overweight (obesity-prone) AA but not EA women were significantly more insulin-sensitive than their never-obese counterparts." (PMID 23298367, 2013). "Similarly in obesity, in intact muscle strips, there is impaired IRS-1 tyrosine phosphorylation and PI-3 kinase activity in response to insulin stimulation." (PMID 23468892, 2013). "Based on the increase in DEP-1 activity in diet-induced obesity – measured under reduced conditions – we hypothesized that DEP-1 plays a role in metabolic changes and insulin signaling." (PMID 23889985, 2013). "In obesity-induced insulin-resistant states, insulin is not able to inhibit the activity of hormone-sensitive lipase in adipose tissues and release FFA into circulation." (PMID 23761785, 2013). "Descriptive statistics of all study participant saliva samples tested for Bone Panel (osteoprotegrin (OPG), leptin, parathyroid hormone (PTH) and insulin), Matrix Metalloproteinase Panel (MMP-2, MMP-8, MMP-9) and Obesity Panel (adiponectin and C-reactive protein (CRP))." (PMID 23577067, 2013). "We have examined the relationships between generalized and regional adiposity and insulin sensitivity in a group of nondiabetic men with varying degree of obesity." (PMID 23691287, 2013). "In conclusion, rosuvastatin exerts pleiotropic effects through a dose-dependent improvement of glucose intolerance, insulin sensitivity and NAFLD and changes the fat distribution from visceral to subcutaneous fat depots in a mouse model of diet-induced obesity." (PMID 23816341, 2013). "With obesity and IR there is increased lipolysis, consequently there is an inappropriate spill over of TAG derived FFAs and these FFAs can activate inflammatory pathways and impair insulin signaling." (PMID 23675368, 2013). "The metabolic phenotype of ClockΔ19 mutants is one of obesity, hyper-insulinaemia, hyper-lipidaemia, glucose intolerance and increased insulin sensitivity, although not all metabolic alterations are observed in mutants on all backgrounds." (PMID 23750248, 2013). "The robust effect of moderate-intensity endurance exercise training stimulating mitochondrial capacity was clearly demonstrated but was not related to obesity or insulin sensitivity." (PMID 23776659, 2013). "We have previously reported that migrant Asian Indians, compared to non-Hispanic white Americans, have excessive insulin resistance relative to their degree of obesity." (PMID 23691287, 2013). "In contrast, formerly overweight (obesity-prone) EA women were 22% less insulin sensitive than never overweight EA women." (PMID 23298367, 2013). "Formerly overweight (obesity-prone) AA women were 43% more insulin sensitive than never overweight AA women (P < 0.05)." (PMID 23298367, 2013). "Therefore, we performed the insulin sensitivity test in the HFD mouse, because of its greater similarity to polygenic pathogenesis of human obesity compared with Zucker fa/fa rat." (PMID 22808093, 2012). "Hyperuricemia was correlated with other components of MetS in one study such as blood pressure, obesity, and immunoreactive insulin, but did not correlate with components such as leptin or blood glucose levels." (PMID 28348676, 2012). "The absence of obesity and hyperglycemia removes two important confounders that can affect insulin action." (PMID 23194380, 2012). "Insulin, androgens and BMI (obesity) are related in women both with and without polycystic ovary syndrome." (PMID 21967243, 2012). "Although the children with poor fitness and obesity had raised fasting insulin, this did not result in raised glucose levels at this age." (PMID 22693553, 2012).
Obesity (continued). "We hypothesize that these factors (FFAs, TNF-α, and resistin) and drug (rosiglitazone) may have a potential regulatory mechanism in obesity through the regulation of LYRM1 mRNA expression, thereby affecting insulin sensitivity." (PMID 22110480, 2012). "These correlations between obesity, insulin, and BCAA may support the notion that the lower BCAA observed in the present study can be explained by reduced postprandial insulin secretion during RB, a topic which warrants further investigation." (PMID 23088297, 2012). "Finally, because diet and exercise are the mainstays of therapy for obesity and T2DM, we systematically reviewed the literature for the effect of diet and or exercise on diminishing ectopic fat stores and restoring insulin sensitivity in obesity and T2DM." (PMID 22675355, 2012). "Many of these effects of obesity operate through the PI3K/ATK/mTOR (e.g., insulin) or LkB-AMPK/mTOR (e.g., adiponectin) pathways, such that obesity affects pathways which may, in turn, support FFM retention." (PMID 22257467, 2012). "According to our data, the increased baseline insulin is much more sensitive in patients with obesity with or without PCOS than the standard OGTT without IRI measurement regarding the carbohydrate metabolism disturbances." (PMID 22262974, 2012). "Participants who subsequently developed MetS had greater obesity, higher triglycerides, lower smoking, and higher proportion of insulin- or oral agent-treated at baseline than those who did not develop the MetS." (PMID 22474593, 2012). "Moreover, we also include its actions on glucose metabolism and insulin release as well as their possible pathophysiological role in metabolic disorders with increasing incidences as T2DM and obesity." (PMID 23162532, 2012). "Interestingly, by rescuing the expression of the kinin B1R exclusively in cells of the adipose tissue, we partially rescue these phenotypes, as well as the increased systemic insulin sensitivity and the resistance against HFD-induced obesity of B1−/− mice." (PMID 23024762, 2012). "The specific isoenergetic HF/HS diet used within the current study had induced obesity but no insulin resistance." (PMID 22781503, 2012). "A previous study, including our group, showed that diet-induced obesity rats submitted to exercise training reduce activation of both the NF-κB and serine 307 phosphorylation of IRS-1, leading to a decreased resistance to insulin." (PMID 23046739, 2012). "NICE guidelines still suggest that most patients without considerable obesity (BMI <35 kg/m2) are probably best managed using insulin therapy." (PMID 22051096, 2012). "In addition, BAT is recognized for its anti-obesity properties given that mice with increased BAT gain less weight, are more insulin sensitive, and are protected from diabetes." (PMID 22509299, 2012). "Mammalian type 1 diabetes is similarly characterized by high blood glucose, the absence of obesity, reduced insulin production, and inadequate suppression of glucagon secretion." (PMID 22761585, 2012). "Muscle GLUT4 protein level is not altered in obesity and T2D, however, its expression levels decline with age, and are related to insulin sensitivity in normal controls." (PMID 22675349, 2012). "This last defect in patients with type 2 DM and obesity has been shown to persist in the fasting state and is not removed after an insulin stimulus with a euglycemic clamp." (PMID 22574901, 2012). "The CYP2E1 has been widely studied in pigs regarding boar taint, however, its relation to porcine lipid metabolism and fatness has never been explored, even if its key role in obesity and insulin resistance phenotypes has been showed in rodents and humans." (PMID 22607048, 2012). "Our findings also reveal that in conditions of low grade inflammation such as obesity, SAA could participate to the metabolic phenotype characterized by adipose tissue inflammation, insulin resistance and fatty acid overflow from adipocytes." (PMID 22532826, 2012).
Obesity (continued). "For example, VEGF plays an important role in the vascularization of the expanding adipose tissue in development or obesity; GRB-14 inhibits insulin action; TFAP2B affects adipokine secretion and adipocyte insulin sensitivity and TBX15 differentiation and lipid accumulation." (PMID 22651247, 2012). "In the present study we found some evidence that, even in this absence of obesity, increased fat stores have the potential to produce a detrimental effect on muscle insulin action." (PMID 21589939, 2011). "They showed that increased insulin levels predict greater LVM in obese persons, independent of relations among insulin, obesity, and BP." (PMID 21911326, 2011). "Despite these limitations, our study demonstrated a consistent and significant relationship among the serum markers of obesity measured (insulin, C-peptide, IGF-1, adiponectin, BMI), supporting the conclusion of a limited relationship between obesity and colorectal cancer survival." (PMID 21081932, 2011). "During obesity, an increase in FFA, which is toxic to pancreatic cells that are sensitive to oxidation and inducing alterations in insulin release, may lead to the development of DM." (PMID 21686173, 2011). "Congruent with the findings of the current study, the association between childhood and adult hsCRP levels in Finns was independent of serum lipids, blood pressure, smoking, obesity indices, and insulin." (PMID 22482065, 2011). "The PASK gene, whereby expression was up regulated in the LBW animals, has been shown to be a metabolic sensor based on mice knock-out studies; mice lacking PASK are resistant to high-fat induced obesity, hepatic steatosis and are resistant to insulin." (PMID 21999700, 2011). "Stress kinases previously demonstrated to negatively influence insulin signaling in obesity were studied for their relationship to insulin action in the non-obese population." (PMID 21589939, 2011). "Our data is therefore suggestive of an accumulation of fat across multiple depots and tissue beds driving a phenotype similar to obesity, rather than a mechanism promoting tissue-specific lipid deposition, that results in insulin resistance." (PMID 21589939, 2011). "Unlike obesity, critical illness evokes adipose tissue accumulation of alternatively activated M2 macrophages, which have local anti-inflammatory and insulin sensitizing features." (PMID 22018099, 2011). "In agreement with a physiological role of these in vitro observations, in a mouse model of obesity, FXR deficiency rather than FXR stimulation attenuated body weight gain and improved insulin sensitivity by extrahepatic FXR effects." (PMID 22110577, 2011). "In addition, it had been demonstrated that plasma FGF-21 levels were elevated in insulin-resistant states (obesity, IGT/IFG, T2DM) and were inversely correlated with both peripheral and hepatic insulin sensitivity." (PMID 22046277, 2011). "More importantly, after the onset of obesity and T2DM, oral treatment with GABA inhibited the continual HFD-induced gain in body weights, reduced the concentrations of fasting blood glucose and improved glucose tolerance and insulin sensitivity in mice." (PMID 21966503, 2011). "Adiposity has a strong negative impact on insulin action in skeletal muscle, so much of the work exploring the mechanisms of insulin resistance have employed human and animal models of obesity." (PMID 21589939, 2011). "SAT and VAT vaspin mRNA expression did not correlate with obesity, glucose metabolism, insulin resistance parameters, blood pressure, other adipokines studied or inflammatory parameters (data not shown)." (PMID 21526992, 2011). "For instance, leucine feeding in mice attenuated high-fat-induced obesity, hyperglycemia and hypercholesterolemia, and an orally administered KAA mixture of leucine, isoleucine, valine, threonine and lysine improved insulin sensitivity in elderly patients with type-2 diabetes." (PMID 20706589, 2010).
Obesity (continued). "Also, in mice with pre-existing obesity, short-term pharmacologic antagonism of CCR2 reduces adipose tissue macrophage content and improves in vivo insulin sensitivity." (PMID 20936118, 2010). "It is also relevant to mention that as Reaven found insulin resistant individuals who were not obese, he did not include obesity as a feature of the insulin resistance syndrome." (PMID 20846382, 2010). "HF diet induced ileal TNF-α mRNA in CONV but not GF mice and this increase preceded obesity and strongly and significantly correlated with diet induced weight gain, adiposity, plasma insulin and glucose." (PMID 20808947, 2010). "From the information gathered regarding their individual functions, we propose that under conditions of stress and obesity, the interactions between SUMO4 and GAPDH play a role in regulating insulin and EGFR signalling to increase vascular complications in diabetic subjects." (PMID 19997558, 2009). "It was previously demonstrated that the genetic effects of variants associated with either insulin secretion (like for GCK, KCNJ11 or TCF7L2) or insulin action (for ENPP1, ADIPOQ or PPARG) may be modulated by the obesity status or adiposity." (PMID 19368707, 2009). "CA3 expression was decreased by leptin but increased by insulin in freshly isolated rat adipose cells, which suggests that the decrease in CA3 expression observed in obesity may be related to hyperleptinemia." (PMID 19689798, 2009). "Although obese adolescents in general are insulin resistant, the degree of obesity is not a major determining factor and together with age, cardiorespiratory fitness, and truncal fat, only 25% of individual variation can be explained." (PMID 19390624, 2009). "PNPLA1 exhibited a modest effect on obesity and PNPLA3 on insulin sensitivity." (PMID 19390624, 2009). "Mice with deficiency in both Cidea and Cideb have higher energy expenditure, enhanced insulin sensitivity and are resistance to high-fat-diet (HFD)-induced obesity and diabetes, suggesting a universal role of Cide proteins in the regulation of energy homeostasis." (PMID 18682832, 2008). "Taken together, these data illustrate a crucial role for PTP1B in insulin and leptin pathways and suggest that abnormal PTP1B activity could lead to insulin resistance and thereby to T2D and to obesity." (PMID 16677372, 2006). "Like in rodents, the human homolog appears as an adipose-specific and obesity-regulated antagonist of insulin action or, conversely, blood/immune cells and not adipocytes are source of resistin." (PMID 17183659, 2006). "Mice lacking DGAT1 have increased energy expenditure and insulin sensitivity and are protected against diet-induced obesity and glucose intolerance." (PMID 16448557, 2006). "In contrast, transplantation of WT adipose tissue into Dgat1-/- mice did not adversely affect their resistance to diet-induced obesity or enhanced response to insulin." (PMID 16448557, 2006). "For the Chinese, the first factor loaded only obesity and explained 19% of the original variance; the third factor loaded primarily obesity, INS, and negative SBP and DBP, and explained about 14% of the original variance." (PMID 16076393, 2005). "Our finding of an association between BMI and both colon and rectum cancers in men supports earlier observations and may be due to the growth-promoting effects of insulin and insulin-like growth factor (IGF-1), both increased in obesity." (PMID 16234822, 2005). "High insulin levels and increased SNS tone are useful for the maintenance of caloric balance, but in the long term they are conducive to CHD, hypertension, sudden death, and obesity as the SNS receptors become down regulated." (PMID 15530168, 2004). "Therefore, the anti-obesity effect of HCRTR2 may be mediated through the regulation of energy metabolism and insulin sensitivity." (PMID 41596924, 2026).
Obesity (continued). "Furthermore, the biological pathways described such as brain inflammation, leaky blood-brain barriers, and insulin resistance are largely based on animal studies or general obesity research rather than direct testing in LC patients." (PMID 41543809, 2026). "Interestingly, insulin increases the expression of UPR markers and activates eIF2α, which is necessary for increasing the protein folding capacity of ER in muscle, and these responses are intact in obesity and T2D." (PMID 42017540, 2026). "Transitioning from obesity to non-obesity may involve metabolic changes, such as improved insulin sensitivity and reduced inflammation, which can positively affect kidney function." (PMID 39894937, 2025). "Additionally, new research suggests that obesity affects the immune system and specific proteins like kallikrein 7 (KLK7), which may interfere with insulin’s ability to regulate blood sugar." (PMID 40427653, 2025). "Over a period of two years with sporadic health check-ups, the patient reported a loss of 2 kg in weight, persistent fatigue, and mild increases in thirst and urine output, without any evidence of insulin resistance characteristics, such as acanthosis nigricans or obesity." (PMID 40303645, 2025). "However, it has also been shown that high-intensity interval exercise does not affect insulin, lipid profile, C-reactive protein, and interleukin-6 in people with overweight or obesity." (PMID 40003575, 2025). "Additionally, studies have shown that insulin signaling in AGRP neurons helps regulate meal size, suggesting that AGRP may play a role in preventing the development of obesity and insulin resistance." (PMID 40531768, 2025). "Conversely, in early-stage or obesity-driven T2D characterized by hyperphagia and rapid gastric emptying, PYY may complement existing incretin therapy through appetite control and improved insulin sensitivity at peripheral sites." (PMID 41228539, 2025). "In obesity and type 2 diabetes, chronic hyperglycemia disrupts GI neuron activity by suppressing AMP-activated protein kinase (AMPK) and enhancing mammalian target of rapamycin (mTOR) signaling, leading to impaired nitric oxide (NO)-mediated insulin sensitivity." (PMID 40452923, 2025). "However, in obesity-induced IR, aberrant IRS-1 phosphorylation impedes insulin signal transduction." (PMID 41154464, 2025). "Since insulin sensitivity closely correlates with weight gain, and both groups developed obesity after 24 weeks of the HFD, this could explain the lack of difference in insulin sensitivity." (PMID 40806018, 2025). "Implicit in this observation is that insulin secretion declines in response to AgRP neuron inactivation in these animals — a finding in sharp contrast to the absence of any detectable change of food intake or obesity." (PMID 40371641, 2025). "Dysregulation of leptin and insulin signaling pathways within brain regions may contribute not only to the development of obesity, but also systemically affect the peripheral organs, thereby manifesting as metabolic diseases involving altered DNA methylation." (PMID 40195216, 2025). "Other benefits of incretins were demonstrated in a retrospective cohort study, n = 1,651,452, mean age 59.8 ± 15.1 years, whose participants had no prior diagnosis of obesity‐associated cancers (OACs), had T2DM, and were prescribed GLP‐1 s, insulin, or metformin." (PMID 41062431, 2025). "Additionally, we did not measure obesity-related markers such as insulin, C-peptide, glucagon, leptin, or cortisol." (PMID 41323348, 2025). "Conversely, two other studies report no changes in (tissue-specific) insulin sensitivity after either seven-day or 14-d oral vancomycin use (different doses) compared to control in males with obesity and insulin resistance and adults with obesity and impaired glucose tolerance, respectively." (PMID 41243448, 2025).